BCL2 (BCL2 apoptosis regulator)
Diseases named in the same sentence as BCL2 in open-access papers (continued):
Sharing a sentence is not in itself a finding about the gene and the disease.
breast carcinoma (continued). "It is worth mentioning that BcL-xL is reported to be a more functional anti-apoptotic protein than Bcl-2 in breast cancer cells." (PMID 39768178, 2024). "Our studies are the first to show that Bcl-2 functional inhibition restores PTX sensitivity in APC mutant breast cancer cells." (PMID 38928449, 2024). "Clinical studies in bioinformatics have indicated a positive correlation between ESR1 and either CCND1 or BCL2 gene expression in all breast cancer patients." (PMID 39202273, 2024). "We investigated the effects of Disarib, a BCL2 specific inhibitor, on breast cancer cells and xenografts." (PMID 38928195, 2024). "Research by Park J R and colleagues found that Huangqin extract (SBGE) acts on MCF-7 breast cancer cells, increasing the sub-G1 phase ratio, inhibiting mitochondrial membrane potential, and inducing cell apoptosis by downregulating Bcl-2 and upregulating Bax." (PMID 38993643, 2024). "In breast cancer cells, ERβ can increase autophagic flux by reducing the expression of BCL-2 and promoting cancer cell death." (PMID 38421826, 2024). "Overexpression of miR-1 in breast cancer decreases cell proliferation, and invasion and induces apoptosis in vitro and in vivo through reduced Bcl-2 expression." (PMID 38813102, 2024). "MiR-34a inhibited the migration, invasion, and proliferation and modulated drug sensitivity in breast cancer cells by affecting antiapoptotic genes Bcl-2 and CCND1 and the Ras family proteins, NOTCH1 and PRKD1." (PMID 38919953, 2024). "To further explore the ability of TMCO1 silencing to promote death in basal breast cancer cells, we performed cell death studies using other basal breast cancer cell lines that have been previously assessed in the context of Bcl-2 inhibition." (PMID 39353922, 2024). "Secretion of IL-10, which is responsible for the regulation of BCL-2 and STAT3 expressions, induces the activation of the IL-10-STAT3-BCL2 pathway in breast cancer, which enhances drug resistance." (PMID 39309874, 2024). "Dendritic cell differentiation is controlled at least by STAT3-binding lncRNA-dendritic cells (lnc-DC) in humans; in breast cancer, lnc-DC can inhibit tamoxifen-induced apoptosis by upregulating antiapoptotic (Bcl2 and Bcl-xL)." (PMID 39335585, 2024). "We used a bioinformatics approach in this study to examine Bcl2 expression and its predictive value in Breast cancer (BC)." (PMID 38223131, 2024). "This compound downregulates Bcl-2 expression significantly, induces mitochondrial dysfunction, and exhibits notable anti-cancer effects in breast cancer cells." (PMID 38785951, 2024). "Anthracycline-based chemotherapy showed pCR benefit of 26.1% (n=1) vs 4.3% (n=1) in Bcl-2- and Bcl2+ breast cancer patients, 35.0% (n=1) vs 8.6% (n=1) in high and low Smac, and 28.3% (n=1) vs 11.5% (n=1) in low and high Survivin." (PMID 38576013, 2024). "Our study demonstrated that Bcl2 is overexpressed in BC and possesses oncogenic properties, and targeting Bcl2 with paclitaxel is potent therapeutic strategy to treat breast cancer patients." (PMID 38223131, 2024). "Our data also evidenced that some YAP/TAZ target genes, such as NF2, AXL, SOX2 and BIRC5, were regulated by Bcl-2 specifically in breast carcinoma model." (PMID 38755629, 2024). "The prognostic relevance, expression pattern, genetic modification, and immunological connection of Bcl2 in the diverse breast cancer subtypes were investigated using the tools GEPIA, Bc GeneExminer, UALCAN, TIMER 2.0, ENRICHR, and TISCH." (PMID 38223131, 2024). "Although OLE-mALG treatment triggered an increase in the pro-apoptotic Bax protein level, anti-apoptotic Bcl-2 protein level was decreased in 3D breast cancer model." (PMID 38722566, 2024). "The reduction in viability induced by BFC1108 correlated with increased Bcl-2 expression in breast cancer cells." (PMID 38329389, 2024).
breast carcinoma (continued). "TIMER2.0 was used to estimate the correlations between ESR1, with a purity adjustment, and the expression of CTSD, EGFR, CCND1, and BCL2 in breast cancer subtypes." (PMID 39202273, 2024). "Around 75% of primary breast cancers overexpress BCL2, providing an opportunity to explore BCL2 inhibitors as a therapeutic option." (PMID 38928195, 2024). "MMPP promoted apoptosis in breast cancer cells via cleavage of caspase-3, caspase-8, and caspase-9 and regulation of Bcl-2 and Bax through the VEGFR2/AKT and PPARγ/PTEN/AKT pathways." (PMID 37942548, 2024). "Leukemia and breast carcinoma cells overexpressing sorcin also showed high expression of Bcl-2, along with decreased level of Bax; upon sorcin silencing, cells show increased Bax, c-fos and c-jun expression, while the level of Bcl-2 is decreased." (PMID 39199583, 2024). "Bcl-2 overexpression is associated with high GSH levels, and the inhibition of GSH synthesis reverses Bcl-2-mediated cisplatin resistance in breast cancer cells." (PMID 39199642, 2024). "Ginestin has shown effects on Akt, NF-κB, matrix metalloproteinases (MMPs), and BAX/Bcl-2 signaling pathways for breast cancer prevention in C57Bl/6 mice." (PMID 39246660, 2024). "Treatment with the ROS-inducing agent paraquat causes an increase in the Bax/Bcl-2 ratio and subsequent apoptosis in breast cancer cells, which has been found to be mediated by the disruption of the Bcl-2/Bax interaction." (PMID 39273204, 2024). "In this study, we identified BFC1108, a small molecule Bcl-2 functional converter, that suppresses primary and metastatic breast cancers in mouse xenograft models." (PMID 38329389, 2024). "It is reported that ITGAV silencing inhibits cell proliferation, invasion, and self-renewal of breast cancer cell lines by altering the expression of BCL2 and PXN (Cheuk, Siu, 2020)." (PMID 38374893, 2024). "A previous study revealed that the miR‐185‐5p/BCL‐2 regulatory axis plays a vital role in the prognosis of breast cancer." (PMID 38037859, 2024). "Nanoparticles were formed by ternary complexing of DP, a targeted ligand-grafted lysine dendrimer peptide, and pDNA expressing shRNA for the bcl-2 gene, which targets the membrane ER (mER) in breast cancer cells." (PMID 39319107, 2024). "This study underscores BCL-2 as a strong, independent indicator of favorable prognosis, with potential to enhance prognostic models in breast cancer." (PMID 39685591, 2024). "BFC1108 suppresses the growth of triple-negative breast cancer xenografts with high Bcl-2 expression and inhibits breast cancer lung metastasis." (PMID 38329389, 2024). "Around 75 % of initial breast cancer cases exhibit increased levels of Bcl-2, with 85 % of these tumours expressing oestrogen receptor (ER) positivity and 50 % expressing HER-2." (PMID 38223131, 2024). "Clinical observations have revealed that approximately 75% of breast cancer tissues exhibit elevated Bcl-2 expression." (PMID 38001342, 2024). "MCF-7 breast cancer cells with high Bcl-2 expression were more sensitive to BFC1108 compared with their vector controls." (PMID 38329389, 2024). "On the other hand, another relevant function of TSLP was further explored in a breast cancer model, demonstrating an increase in antiapoptotic molecules, such as Bcl-2 and Bcl-x." (PMID 38557942, 2024). "The study demonstrated that luteolin and paclitaxel have a synergistic anticancer effect on breast cancer cells by reducing cell viability, inducing significant morphological changes, and downregulating the BCL-2 anti-apoptotic gene." (PMID 39176367, 2024).
breast carcinoma (continued). "This combination treatment of CRISPR-mediated APC knockout MDA-MB-231 cells resulted in alterations in apoptosis, suggesting that Bcl-2 inhibition restores PTX sensitivity in APC knockout breast cancer cells." (PMID 38928449, 2024). "The capability of the nanoparticles to induce apoptosis in MCF-7 breast carcinoma cells was investigated via intracellular ROS analysis, Bax/Bcl-2 analysis, antioxidant enzyme levels, and Hoechst staining." (PMID 39458783, 2024). "The transcript expressions of CTSD, EGFR, CNND1, and BCL2 in breast cancer patients can be observed in the box plots." (PMID 39202273, 2024). "Previous studies have demonstrated that downregulation of BCL2 correlates with improved disease-free survival (DFS) in breast cancer patients." (PMID 38978099, 2024). "Erianin also up-regulated the expression of caspase-3, -7, -9 in breast cancer cells, and altered the ratio of Bcl-2/Bax to induce cell apoptosis." (PMID 39605083, 2024). "The scientists noted a significant inactivation of the anti-apoptotic protein Bcl-2 and the activation of effector caspase-3 and/or 7 within the breast cancer cells." (PMID 38792101, 2024). "The results showed that these NPs significantly downregulated hTERT, Bcl-2, cyclin D1, and survivin, while upregulating caspase-3, caspase-7, and Bax in breast cancer cells, thereby enhancing the antitumor therapeutic effect." (PMID 39555093, 2024). "Proguanil treatment upregulated apoptotic markers (Bax, p-H2AX, cleaved-caspase 3, 9, cleaved PARP) and downregulated anti-apoptotic proteins (bcl-2, survivin) in breast cancer cell lines." (PMID 38473234, 2024). "In a study involving human breast cancer BCap-37 cells, emodin was found to induce apoptosis by lowering the Bcl-2/Bax ratio and increasing the concentration of cytochrome c in the cytoplasm." (PMID 39272454, 2024). "•Targeting BCL2 in combination with other therapeutic drugs will dramatically improve Breast cancer patients' responses to therapy and prevent the emergence of chemoresistance." (PMID 38223131, 2024). "Among the genes regulated by Bcl-2 in both melanoma and breast carcinoma models we identified CTGF, CCND3, TEAD2, FST, MYC and TP73." (PMID 38755629, 2024). "Clinical trials focusing on BH3 mimetics (e.g., ABT737/199) in combination with standard breast cancer therapeutic drugs (e.g., tamoxifen) will undoubtedly promote the utilization and progression of the Bcl-2 apoptotic pathway in breast cancer treatment." (PMID 38001342, 2024). "At the same IC50 concentration, the combination of luteolin and paclitaxel resulted in a significant downregulation of BCL-2 mRNA expression in breast cancer cells compared to luteolin alone." (PMID 39176367, 2024). "It is reported that ITGAV silencing inhibits cell proliferation, invasion and self-renewal of breast cancer cell lines by altering the expression of BCL2 apoptosis regulator (BCL2) and paxillin (PXN)." (PMID 38374893, 2024). "The anticancer effects of BFC1108 were further tested in a breast cancer xenograft mouse model using MDA-MB-231 cells expressing Bcl-2 and in a breast cancer lung metastatic model." (PMID 38329389, 2024).
breast carcinoma (continued). "In silico data from computational docking of FGF19 and BCL-2 proteins showed that they play significant roles in hepatocellular and breast cancer development, respectively." (PMID 39334936, 2024). "Beyond its role in intrinsic apoptosis, ZKSCAN3 also possesses the ability to activate the extrinsic apoptosis pathway, as evidenced by its activation of the Bcl2 signaling pathway and induction of apoptosis in bladder and breast cancer." (PMID 39519085, 2024). "METTL3 promotes breast cancer (BC) promotion and accelerates apoptosis by targeting the apoptosis inhibitor B-cell lymphoma-2 (Bcl-2)." (PMID 38711100, 2024). "Since tucatinib was recently introduced for treatment of HER2+ breast cancers, and Bcl-2 is suggested to play a role in this form of cancer, we wanted to test tucatinib and venetoclax in vivo." (PMID 36706086, 2023). "BCL-2 has been reported to be frequently expressed in breast cancer and can reduce the effectiveness of chemotherapy." (PMID 37193964, 2023). "GCR and its downstream targets, SGK1 and Bcl-2, are critical for several biological processes influencing breast cancer growth and progression." (PMID 37370761, 2023). "Research shows that TGF-B2 promotes the survival of breast cancer stem cells by upregulating the expression of the anti-apoptotic protein Bcl-2." (PMID 37176095, 2023). "The FA-functionalized Amy-F alone or prior RT abrogated proliferation, induced cell cycle arrest at pre-G1 and G2/M, and increased apoptosis as revealed by lower BCl-2 levels and higher caspase-3 levels of breast cancer cells." (PMID 37210478, 2023). "The results of western blotting (at protein level), and RT-PCR (at gene level) assays showed that DOX-loaded NPs induced apoptosis in MDA-MB-231 breast cancer cells via Bcl-2/Bax, caspases 3, 7, and 9 dependent inherent mitochondrial apoptosis routes." (PMID 38110480, 2023). "↑ Apoptosis, ↑ Bax proteins, and caspase-3 activity, ↓ Bcl-2 protein in breast cancer cells (Hs578T, MCF-7, and MDA-MB-231)Data demonstrated that amygdalin exerted cytotoxic effect." (PMID 37762572, 2023). "BCL2 gene expression has been extensively studied in various types of cancer, including breast cancer, colorectal cancer, bladder cancer, lymphoma, and acute myeloid leukemia (AML)." (PMID 38067251, 2023). "A study of the treatment combining antisense BCL-2 with HER2 oligonucleotide in different breast cancer cell lines also showed emerging results, not only suppressing the expression of BCL-2 and pAKT, but also enhancing anticancer drug sensitivity." (PMID 37237509, 2023). "The main objective of this study is to evaluate the expression of SGK1 and Bcl-2 in breast cancer tissue." (PMID 37370761, 2023). "In another study, a PEI-based NP system was synthesized to codeliver doxorubicin, aspirin, and Bcl-2 siRNA to colorectal and breast cancer cells." (PMID 37511335, 2023). "Studies have shown that breast cancer patients with positive BCL2 expression tend to have better overall survival and disease-free survival." (PMID 38067251, 2023). "Diacerein is another approved drug that has been reported to exert anti-proliferative effects on breast cancer cell lines, induced apoptosis and decreased the expression of BCL-2." (PMID 37193964, 2023). "To determine the underlying molecular mechanism of cell death, we analyzed how treatment of breast cancer cell lines affected the expression of genes involved in apoptosis, such as BCL-2, BAX, Cas-3, Cas-8, and Cas-9." (PMID 36770598, 2023). "In this context, MTHFD2 also regulates apoptosis-related genes, including Bcl2 and Bax, to affect apoptosis in breast cancer." (PMID 36726381, 2023).
breast carcinoma (continued). "In particular, we previously reported that Bcl-xL and Bcl-2 increase the NF-kB DNA binding activity with a mechanism dependent to IKKα/β and IKBα phosphorylation in glioblastoma and breast cancer." (PMID 37488586, 2023). "Western blot for visualisation proved the ability of compound 7f to induce the expression of proapoptotic caspases and Bax proteins in MCF-7 breast cancer cell line beside its ability to diminish the expression of antiapoptotic Bcl-2 protein." (PMID 36382444, 2023). "We also evaluated the correlation of GCR, SGK1, and Bcl-2 with overall survival and breast cancer-specific survival." (PMID 37370761, 2023). "In breast cancer, miR-181a-5p can significantly downregulate BCL2, leading to breast cancer cell apoptosis." (PMID 36800936, 2023). "In the same context, the silencing of Bcl-2 was found to induce autophagic cell death in MCF 7 breast cancer cells." (PMID 37504291, 2023). "It has also been proven that BCL2 expression is an independent indicator of favorable prognosis for all types of breast cancer in the early stages." (PMID 38003498, 2023). "The expression levels of ERBB2, CCND1, and BCL2 were significantly higher in the breast cancer component than in the FAs." (PMID 37328469, 2023). "Regarding VCR in breast cancer cells, this effect has already been described where Bcl2 hyperphosphorylation prevents its binding to Bax." (PMID 37960113, 2023). "Ginsenosides promote apoptosis in breast cancer cells by regulating the Bcl-2/Bax/Caspase-3 signaling pathway." (PMID 37818185, 2023). "We measured the expression of SGK1 and Bcl-2, in respective breast cancer tissue arrays, from a multiracial cohort of breast cancer patients." (PMID 37370761, 2023). "The expression of BECN1 in breast cancer tissues has been found to be negatively correlated with that of BCL‐2." (PMID 36852470, 2023). "This induction of apoptosis is mediated in the two breast-cancer cell lines through the mitochondrial pathway via the downregulation of Bcl-2/Bax." (PMID 37298600, 2023). "The most common BCL-2 polymorphism, BCL-2 −938C>A in the promoter region of the gene, has been associated with predisposition to breast cancer." (PMID 38003498, 2023). "As a result, a significant increase in the Bax/Bcl-2 ratio was observed, supporting the claim that the tested compounds can improve the therapeutic response in breast cancer." (PMID 37591917, 2023). "Previous reports have also indicated that myricetin induces apoptosis by increasing the Bax/Bcl-2 ratio in breast cancer and lymphoma." (PMID 38026996, 2023). "Compound 7f was proven to induce the expression of proapoptotic caspases and Bax proteins in MCF-7 breast cancer cell line beside its ability to diminish the expression of antiapoptotic Bcl-2 protein." (PMID 36382444, 2023). "A cell viability assay, a flow cytometer analysis of apoptosis and cell cycle phases, and protein activity of BAX and Bcl-2 were performed on two human breast cancer cell lines—MCF-7 and MCF-7/DOX." (PMID 36672406, 2023). "For instance, the induction of apoptosis via Bax upregulation and Bcl-2 downregulation was found in MCF-7 breast cancer cells treated with quercetin." (PMID 37373017, 2023).